MCM2 (minichromosome maintenance complex component 2)
Description:
Acts as a component of the MCM2-7 complex (MCM complex) which is the replicative helicase essential for 'once per cell cycle' DNA replication initiation and elongation in eukaryotic cells. Core component of CDC45-MCM-GINS (CMG) helicase, the molecular machine that unwinds template DNA during replication, and around which the replisome is built. The active ATPase sites in the MCM2-7 ring are formed through the interaction surfaces of two neighboring subunits such that a critical structure of a conserved arginine finger motif is provided in trans relative to the ATP-binding site of the Walker A box of the adjacent subunit. The six ATPase active sites, however, are likely to contribute differentially to the complex helicase activity. Required for the entry in S phase and for cell division. Plays a role in terminally differentiated hair cells development of the cochlea and induces cells apoptosis.
Synonyms: BM28; CCNL1; CDCL1; KIAA0030; D3S3194; cdc19; DFNA70; MITOTIN
Tractability: Small molecule: a structure with a bound ligand is known. PROTAC: UniProt records ubiquitination sites on it; ubiquitination databases record sites on it; its protein half-life has been measured.
Target class: Enzyme; Hydrolase
Gene: Protein-coding gene on chromosome 3 (127,598,223 to 127,622,437, forward strand). Ensembl gene ENSG00000073111.
Subcellular location: Nucleus; Chromosome
Subcellular location (Human Protein Atlas): Nucleoplasm; Cytosol; Primary cilium; Vesicles
Pathways (Reactome):
DNA Replication: Activation of the pre-replicative complex; Assembly of the pre-replicative complex; Orc1 removal from chromatin; Switching of origins to a post-replicative state; Unwinding of DNA
Cell Cycle: Activation of ATR in response to replication stress
Developmental Biology: Regulation of MITF-M-dependent genes involved in DNA replication, damage repair and senescence
Gene Ontology:
Molecular function: ATP hydrolysis activity; histone binding; protein binding; 3'-5' DNA helicase activity; DNA binding; single-stranded DNA binding; single-stranded DNA helicase activity; ATP binding; DNA helicase activity; DNA replication origin binding; enzyme binding
Biological process: apoptotic process; cochlea development; DNA replication; DNA replication initiation; double-strand break repair via break-induced replication; mitotic DNA replication initiation; regulation of DNA-templated DNA replication initiation
Cellular component: chromatin; chromosome, telomeric region; CMG complex; cytoplasm; MCM complex; nucleolus; nucleoplasm; nucleus; chromosome; nuclear lumen; nuclear origin of replication recognition complex
Genetic constraint (gnomAD): Loss-of-function variants: 49 observed, 88.06 expected, observed/expected ratio (o/e) 0.56, 90% interval 0.44 to 0.71. The upper end of that interval is the gene's LOEUF score, 0.71, which puts it in group 2 of 6, group 1 being the genes least tolerant of losing a copy. Missense variants: 1,036 observed, 1,311.6 expected, observed/expected ratio (o/e) 0.79, 90% interval 0.75 to 0.83. Synonymous variants: 475 observed, 509.28 expected, observed/expected ratio (o/e) 0.93, 90% interval 0.86 to 1.01.
Gene-disease validity (ClinGen):
ClinGen rates the evidence that MCM2 causes each of these diseases.
nonsyndromic genetic hearing loss (autosomal dominant): Limited.
Homologues: Orthologues: chimpanzee MCM2 (100% identical), macaque MCM2 (99% identical), rabbit MCM2 (98% identical), dog MCM2 (97% identical), guinea pig MCM2 (97% identical), pig MCM2 (97% identical), rat Mcm2 (96% identical), mouse Mcm2 (96% identical), tropical clawed frog mcm2 (86% identical), zebrafish mcm2 (84% identical), Drosophila melanogaster Mcm2 (64% identical), Caenorhabditis elegans mcm-2 (55% identical). Paralogues in human: MCM3 (27% identical), MCM4 (26% identical), MCM9 (26% identical), MCM5 (26% identical), MCM7 (25% identical), MCM6 (24% identical), MCM8 (24% identical), MCMDC2 (11% identical).
Diseases named in the same sentence as MCM2 in open-access papers:
MCM2 is named in the same sentence as 184 diseases in open-access papers, as found by Europe PMC text mining. Sharing a sentence is not in itself a finding about the gene and the disease. The quoted sentences say what the papers report.
breast cancer (56 papers, 2005 to 2026). A primary or metastatic malignant neoplasm involving the breast. "In the present report, we found that expression of Cdc6 and Cdt1 was positively correlated with MCM2-7 overexpression, while high levels expression of Cdc6 and Cdt1 were associated with poor prognosis in breast cancer patients." (PMID 28428557, 2017). "In breast cancer, high expression of MCM2 is associated with several clinicopathological parameters, such as advanced tumor grade, advanced stage, and poor prognosis." (PMID 26430873, 2015). "In breast cancers, increasing tumour grade is associated with increased Ki67, Mcm2 and geminin expression." (PMID 16278669, 2005). "Elevated expression of MCM2 in breast cancer patients is tightly linked to a poor prognosis." (PMID 41020311, 2025). "The level of MCM2 expression was tightly associated with patient survival in breast cancer." (PMID 36303105, 2022). "High expression of MCM2 was associated with poor survival in breast cancer patients." (PMID 33816496, 2021). "In breast cancers, increasing neoplasm grade is associated with increased MCM2 expression." (PMID 21943228, 2011). "Since Cdc6, Cdt1 and Orc1 work cooperatively with MCM2-7 to initiate DNA replication, in our current study we have investigated whether there are associations between these three genes and clinicopathological parameters or expression of MCMs in breast cancer." (PMID 28428557, 2017). "SSBP1, TXNRD1, SLC25A5, DDOST, SEH1L, and MCM2 had a significant effect in at least 50% of breast cancer cell lines in the CRISPR-Cas9 and/or RNAi screening data." (PMID 37445737, 2023). "Bioinformatic analysis using TCGA and oncomine cohort further confirmed the potential of MCM2 to be a prognostic biomarker in breast cancer." (PMID 36303105, 2022). "According to a breast cancer cohort (n = 221), patients with a higher level of MCM2 LI experienced early relapse and shortened OS." (PMID 36303105, 2022). "In breast cancer, the mRNA and protein levels of MCM2 are increased and tend to increase gradually as the malignancy of tumors increases." (PMID 34993142, 2021). "MCM2 has been found to be overexpressed in several cancers such as oral, gastric, colon, lung and breast cancer." (PMID 33499054, 2021). "Six independent breast cancer patient cohorts, which we have used for studying MCM2-7 genes previously using the Affymetrix platform, were included in the present study." (PMID 30135378, 2018). "Future studies using immunohistochemistry should be directed towards utility of Ki67 and MCM2 in choosing the appropriate adjuvant therapy in early breast cancer cases." (PMID 26205655, 2015). "According to another NCBI GEO database (accession number: GDS4051), the expression of MCM2 is higher in the tamoxifen-resistant breast cancer cell line MCF7 than in tamoxifen-sensitive MCF7 cells." (PMID 26430873, 2015). "MCM-2 has been reported for its use as a strongly independent prognostic marker in breast cancer and non-small cell lung cancer, in addition to the standard proliferation marker Ki-67." (PMID 25385471, 2015). "MCM2 has a significantly higher frequency of expression in breast cancer nuclei than Ki67 and Geminin." (PMID 26205655, 2015). "In vitro, Hph-1-gp70 was rapidly and effectively introduced into breast cancer cell lines, in which it bound to MCM2 in the cytoplasm and enhanced DNA damage-induced apoptosis in cells expressing high levels of MCM2." (PMID 26430873, 2015). "To generate a cancer therapy model using gp70, we introduced the gp70 protein into the cytoplasm of murine breast cancer cells that express high levels of MCM2 by conjugating the protein transduction domain (PTD) of Hph-1 to gp70 (Hph- 1-gp70)." (PMID 26430873, 2015). "In breast cancers, it appears to be a strong independent prognostic marker and the degree of MCM2 immunoreactivity has been correlated with high histologic grade." (PMID 21785684, 2011).
breast cancer (continued). "It is of note that a large number of breast cancers (phenotype II), 24% of all tumours, displayed an in-cycle phenotype (Mcm2 >30%) but expressing geminin levels below 7%, indicative of a G1-delayed or -arrested state." (PMID 19240714, 2009). "The particular replication phenotype observed in breast cancer is entirely in keeping with the hierarchical stem cell model of tumour growth, the uncoupling of Mcm2 expression with geminin and Ki67 expression increasing with a higher degree of differentiation." (PMID 16278669, 2005). "It has also been shown that MCM2 overexpression is a poor prognostic factor in glioma, hepatocellular cancers, non-small cell lung cancer, acute lymphocytic leukemia, renal cell cancer and breast cancer." (PMID 34144903, 2022). "However, they have reported MCM2 as a useful marker for distinguishing the aggressive-type HER2-amplified breast carcinomas (with high malignancy grade) from HR-negative subtypes." (PMID 35125121, 2022). "Similarly, MCM2 has been reported to be a potential biomarker of the diagnosis and prognosis of breast cancer." (PMID 34859821, 2021). "Interestingly, the expression of CCNE1 and MCM2 was also significantly inhibited as Roquin1 increased in 1006 human breast cancer samples (Oncolnc.org/)." (PMID 33228782, 2020). "MCM2 could be used as a prognostic marker for various malignancies, such as cervical carcinoma, oral squamous cell carcinoma, breast cancer, and gastric cancer." (PMID 33505310, 2020). "Notably, higher levels of CCNE1 and MCM2 negatively correlated with poor survival of patients with breast cancer." (PMID 33228782, 2020). "Firstly, MCM2 positive cells represents the proliferating breast cancer cells." (PMID 33024414, 2020). "Overexpression of MCM2-7 genes correlated with poor prognosis in breast cancer patients." (PMID 28428557, 2017). "A MCM2-targeted strategy might be an effective therapy for the treatment of highly malignant breast cancers." (PMID 28460433, 2017). "Therefore, to examine the expression level of MCM2 in CD133-high breast cancer cells, we separated and enriched CD133-high cells from other FM3A cells." (PMID 26430873, 2015). "We tested whether the PKR and Chk1 inhibitors would alter cell growth and inhibit Mcm2 phosphorylation in the HCC1954 breast cancer cell line, which would be strong evidence that they inhibit DDK in cells." (PMID 25412417, 2014). "Furthermore, research has demonstrated the elevated expression of MCM2 in various cancers, including breast cancer and hepatocellular carcinoma, suggesting that MCM2 may represent a viable therapeutic target for numerous cancer types." (PMID 40282196, 2025). "The top three genes (WDR62, CDT1 and MCM2) positively correlated with POLD1 expression play important roles in cell proliferation and apoptosis, and their upregulation has been proved to be associated with tumors development and worse prognosis, such as breast cancer and lung adenocarcinoma." (PMID 35189839, 2022). "For instance, it is evident that the MCM2 expression correlates with the malignant status and regulates the proliferation and cell cycle of lung squamous cell carcinoma, renal cell carcinoma, prostate cancer, breast cancers, brain tumors, lymphoma, and gastrointestinal tumors." (PMID 35125121, 2022). "Moreover, the overexpression of SAA1 and the resulting inhibition of autophagy promoted proliferation in the two breast cancer cell lines, evident in our results for the DNA replication licensing factor, MCM2, and cell viability as an indication of proliferation." (PMID 36248994, 2022). "MCM2 was reported to be expressed more frequently than the published marker Ki-67, indicating that it could be a promising independent prognostic marker in breast cancer." (PMID 35693940, 2022). "In addition to Ki-67, MCM2 expression also seems to have prognostic value in breast cancer." (PMID 31446607, 2020).
breast cancer (continued). "Therefore, an MCM2-targeted strategy using Hph-1-gp70 treatment to induce DNA damage might be a successful therapy for highly malignant breast cancers such as TNBC and for the eradication of CSC-like cells from breast cancer tissue." (PMID 26430873, 2015). "The evidences include: overexpression of MCM2 in gastric tumors predicted poor prognosis in the patients; knock down of HJURP reduced the sensitivity of breast cancer patients to radiation treatment; the loss of CHD8 may be an indicator for biological aggressiveness in gastric cancer." (PMID 25390899, 2014). "To date, most studies have focused on MCM2 expression, for example, in oral squamous cell carcinomas, prostate cancer and ovarian serous neoplasms chondrosarcoma, oligodendroglial tumours, oesophageal neoplasm, renal cell carcinoma, breast cancer, endometrial carcinoma and thyroid carcinoma." (PMID 16189522, 2005). "For example, MCM2 is regarded as a novel proliferation biomarker for oligodendroglioma, ESCC,239 and breast cancer." (PMID 36776764, 2023). "Knockdown of MCM2 abolishes DNA damage in ESCC cells, interfering with DNA replication in breast cancer cells." (PMID 36776764, 2023). "MCM2 and MCM3 have also been reported to have a role in DNA repair mechanisms in breast cancer, and these genes have also been reported as predictors of other NAC response predictive models." (PMID 35205629, 2022). "The result showed that the protein expression of TUBB3, MCM2, FN1, S100A7, and TFF1 was increased, and the protein expression of MYOC was downregulated in luminal A breast cancer, which was consistent with the result of RNA expression." (PMID 35692369, 2022). "Issac MSM and his colleagues indicated that the expression of MCM2, MCM4, and MCM6 was obviously increased in breast cancer compared to that in corresponding para-cancerous tissues." (PMID 34178669, 2021). "For instance, in breast cancer, MCM2, MCM4 and MCM6 can help distinguish breast cancers with different histological grades." (PMID 34859821, 2021). "Our research group aimed to test the role of MCM2, Cyclin A and PHH3 as potential biomarkers predicting response to treatment and clinical outcome of locally advanced breast cancer." (PMID 31446607, 2020). "Down-regulated expression levels of MCM2 (mini-chromosome maintenance complex component 2), PARP1, and BRCA1 (breast cancer type 1) genes in CBD-treated HNSCC were confirmed by quantitative real-time RT-PCR and then compared with the RNA-seq results." (PMID 33244087, 2020). "Expression of MCM2 and MCM7 are positively correlated with the Ki67 proliferation marker in prostate cancer, breast cancer, colon cancer, ovarian cancer, lung, and bladder cancer." (PMID 30937307, 2019). "Among them, 5 (TOP2A, HER3, CDC25B, MCM2 and TUBB) are from breast cancer cell lines and, in particular, HER2 positive cells (ZR7530 is [ER+PR−]HER2+, HCC2218 and BT474 are [ER−PR−]HER2+78)." (PMID 28754978, 2017). "We found that MCM2 and MCM3 expression were negatively correlated with patient OS in breast cancer and lung cancer." (PMID 28460433, 2017). "In the present study, we analyzed the expression of MCM2 in HER2, luminal, luminal/HER2, and TN subtypes of human breast cancer." (PMID 26430873, 2015). "It was noteworthy that the PKR inhibitor blocked the growth of HCC1954 breast cancer cells, induced apoptosis, and inhibited DDK-mediated Mcm2 phosphorylation nearly as well as the lead DDK inhibitor PHA-767491." (PMID 25412417, 2014). "Protein expression profiles were generated for Ki67, Mcm2, geminin, HER-2, ER and PR in a series of reduction mammoplasty (n=18) and breast cancer specimens (n=120), and compared to clinicopathological parameters." (PMID 16278669, 2005).